SOX2 (SRY-box transcription factor 2)
Diseases named in the same sentence as SOX2 in open-access papers (continued):
Sharing a sentence is not in itself a finding about the gene and the disease.
cancer (continued). "This study investigates the clinical relevance of SOX2 protein expression in early stages of oral carcinogenesis as a cancer risk biomarker, and also its impact on prognosis and disease outcome at late stages of OSCC progression." (PMID 31640140, 2019). "YY1 has been associated with a regulatory loop with cancer stem cell transcription factors (SOX2, OCT4, BMI1) during the cross-talk between the NF-kB/PI3K/AKT pathways." (PMID 31867044, 2019). "SOX2 expression was also found to be a significant predictor of risk of cancer development (HRs of 6.13 and 5.75 depending on the cut-off used)." (PMID 31640140, 2019). "Stemness of CSCs has been proved to be associated with massive cancer stem markers, such as Bmi1 and Sox2." (PMID 31119150, 2019). "The acquisition of metastatic phenotypes of various cancers has been linked to the alterations of SOX2 expression." (PMID 30186173, 2018). "As H19 play a crucial role in embryogenesis and controls the expression of two major pluripotency factors—Oct4 and Sox2, it promotes cancer stemness, which is associated with poor prognosis in cancer patients." (PMID 30154386, 2018). "Instead, under hypoxia, HIF1α stabilization, despite the presence of SOX2, likely represents the leading factor that causes cancer cell metabolic switch to anaerobic glycolysis." (PMID 30466459, 2018). "Chemo-resistant cancer cells that appear to preferably exploit oxidative metabolism, have been also associated with enhanced SOX2 expression in gastric, lung, prostate, colorectal, and breast cancers." (PMID 30466459, 2018). "The significant genes implicated pathways regulated by SOX2 had relation with cancer-related pathways including PI3K–AKT." (PMID 30108202, 2018). "VEGF/VEGFR2 axis-established autocrine loop consisting of STAT3, Myc and Sox2 which implicated in enhancement of cancer stem-like cell phenotype in TNBC." (PMID 29455658, 2018). "In MCF7 and ZR751, two estrogen receptor-positive BC cell lines, Sox2 is directly implicated in conferring the cancer stem-like features in RR cells, since siRNA knockdown of Sox2 in these cells was found to significantly decrease these properties." (PMID 29401647, 2018). "Increasing evidence strongly suggests that SOX2 is implicated in regulating the development of various malignant tumors, including glioblastoma, small-cell lung cancer, and nasopharyngeal carcinoma." (PMID 30108202, 2018). "For instance, several stemness markers, such as OCT4, C-MYC, KLF4, NANOG, SALL4, and SOX2 are reported to be highly expressed in various cancers and associated with poor clinical outcomes of patients." (PMID 29747452, 2018). "The F3.EGFRviii cell line was highly tumorigenic in vitro and showed high ERK1/2 activity as well as expression of a variety of genes associated with cancer stemness, such as SOX2 and NANOG, under spheroid culture conditions." (PMID 28830458, 2017). "Since 2006, SOX2 has been implicated in growth, tumorigenicity, drug resistance, and metastasis in at least 25 different cancers, including cancers of the ovary, lung, skin, brain, breast, prostate, and pancreas." (PMID 28388544, 2017). "Overexpression of 3q26 encoded genes SEC62 and SOX2 was detected in various cancers, including HNSCCs, indicating their potential function as oncogenes." (PMID 28002801, 2017). "SOX2 has been shown to promote the survival of cancer cells in vivo and has been linked to lens cell survival in Astyanax surface fish, but a role for SOX2 in cell survival during mammalian organogenesis has not been reported." (PMID 28623666, 2017). "OCT-4, NANOG and SOX-2 contribute to the hallmark characteristics of stem and putative cancer stem cells by activation of target genes that encode pluripotency and self-renewal mechanisms." (PMID 29238047, 2017). "The association of SOX2 and miRs in specific cancers has been inferred predominately from the correlation between elevated SOX2 expression and low miR expression." (PMID 28388544, 2017).
cancer (continued). "SOX2 activity has been found to be associated with the maintenance of the undifferentiated state of cancer stem cells." (PMID 29137410, 2017). "3q26 amplification represents a highly frequent chromosomal alteration in HNSCCs and encodes the genes SEC62 and SOX2, which have both been shown to be overexpressed in various cancers, including HNSCCs, and to affect the metastatic potential of cancer cells." (PMID 28002801, 2017). "In HPV-associated cancers stem cell markers Oct4, Sox2 (in cervical cancers), and Lrig1 (in head and neck squamous cell carcinomas) have been reported and proposed as potential biomarkers." (PMID 28805675, 2017). "In conclusion, we found that positive Sox2 expression was associated with worse survival in patients with cardiac gastric cancer and earlier cancer stages (Stages I and II)." (PMID 28046028, 2017). "Although Sox2 was first shown to regulate the transcription of FGF4 in mouse embryonal carcinoma cells, its importance was firmly established with the discovery that knocking out both alleles of Sox2 results in embryonic lethality in mice." (PMID 28388544, 2017). "Given the association reported for SOX2 in drug-resistance in several other cancers, we also examined how changes in the levels of SOX2 influence the responses of PDAC cells to MEKi and AKTi used in clinical trials." (PMID 27145457, 2016). "SOX2 expression has been associated with tumors of high grade (poorly differentiated) in different cancers." (PMID 27411517, 2016). "Sex-determining region Y (SRY)-box 2 (SOX2) is a transcription factor whose activity has been associated with the maintenance of the undifferentiated state of cancer stem cells in several tissues, including the brain." (PMID 27822457, 2016). "A number of studies have been performed to explore the associations of cancer cell stem cell markers, such as SOX2 and Nestin, with clinical parameters and prognosis in various types of cancers including NSCLC." (PMID 27150062, 2016). "SOX2 has been linked to apoptotic resistance and shown to facilitate cell cycle progression in certain types of cancers." (PMID 26969300, 2016). "On the contrary, SOX2 upregulation has been linked to the development and maintenance of several types of cancers." (PMID 27822457, 2016). "SOX2 is also implicated in the cancer stem cell phenotype and development of chemo-resistance in GBM." (PMID 27791206, 2016). "SOX2 is not only essential for normal stem cell function, it has also been implicated in over 20 different cancers, including cancers of the brain, breast, ovary, lung, skin, prostate and pancreas." (PMID 27145457, 2016). "In AOE cells, luciferase reporter assays further revealed that miR-145 directly targets the 3′ UTR regions of Oct4 and Sox2 and overexpression of Sox2/Oct4 effectively reversed miR-145-regulated cancer stemness-associated phenomenas." (PMID 27557511, 2016). "The role of SOX2 as a transcriptional regulator in critical signaling pathways has been implicated in malignant progressions in various human cancers." (PMID 26969300, 2016). "Sox2 has also been implicated in conveying chemoresistance to cancer stem cell-like cells in other cancers through ABCG2 expression levels." (PMID 25889105, 2015). "The function of SOX2 in apoptosis-resistant nature of cancer cells and its underlying mechanism still need to be explained." (PMID 28983346, 2015). "In this study we profiled the SOX2-linked miRNAome and its associated regulatory network in pluripotent and nullipotent cancer stem cells." (PMID 25156079, 2014). "DDX3X expression was associated with upregulation of Sox2 and increase of cancer cells exhibiting CSC-like phenotypes, such as anchorage-independent proliferation, strong expression of CD44, and aldehyde dehydrogenase (ALDH)." (PMID 25343452, 2014).
cancer (continued). "Significantly, development of tamoxifen resistance implies loss of ER transcriptional activity and elevated Sox2 expression, leading to Wnt signalling activation and enrichment of the cancer stem cell population." (PMID 24178749, 2014). "Like many other developmental regulatory factors, the dysregulated expression of SOX2 genes has been implicated in a number of human cancers." (PMID 25006803, 2014). "SOX2 is intricately involved in many cancer-associated processes such as cell proliferation, evading cellular apoptosis and metastasis via interactions with EGFR signaling and several other oncogenic pathways and processes." (PMID 25114775, 2014). "SOX2 has been shown to be associated with numerous cancer types, even described in some cases as an oncogene, and controls cancer cell physiology via promoting oncogenic signaling and maintaining cancer stem cells." (PMID 25114775, 2014). "Our result confirms that SOX2 also plays an important role in the progression of cancers caused by lymphogenic metastasis." (PMID 24376714, 2013). "Collectively, these results demonstrate an unprecedented connection between p27 and Sox2 relevant for reprogramming and cancer and for understanding human pathologies associated with p27 germline mutations." (PMID 23217425, 2012). "Other studies have also shown that Sox2 or Oct4 over-expression is associated with poor prognosis in diverse cancers." (PMID 22837720, 2012). "SOX2 has been reported to be overexpressed in malignancies, and overexpression of SOX2 has been associated with immunity towards autologous antigens in cancer patients." (PMID 22190969, 2011). "SOX2 has also been implicated in several cancers including gastric cancer, breast cancer, pancreatic cancer, pulmonary non-small cell and neuroendocrine carcinomas." (PMID 21211035, 2011). "Moreover, high SOX2 expression is often linked to drug resistance and poor patient prognosis, establishing it as a compelling biomarker for cancer diagnosis and treatment monitoring." (PMID 40674376, 2025). "SOX-2, a transcription factor, is closely linked with the stem-like properties of cancer cells." (PMID 40011711, 2025). "In some cancers, NF-κB activity is linked to Sox2 expression and maintenance of cancer stem cells." (PMID 40568085, 2025). "Similarly, overexpression of Sox2 has been linked to increased cancer invasion, resistance to radiation, and chemotherapy, ultimately leading to a poor prognosis." (PMID 40387464, 2025). "Mechanistically, Wnt5a derived from cancer-associated fibroblasts promotes Hedgehog-mediated SOX2 expression in PCa cells, showing that palmitate and cholesterol induce SOX2 expression through cancer–stromal interactions involving Hedgehog signaling and non-canonical Wnt signaling." (PMID 40821114, 2025). "Furthermore, the up-regulation of SOX2 and gene amplification are closely linked to the initiation and progression of various cancer types." (PMID 39976818, 2025). "Additionally, the high expression of cancer stem cell markers such as SOX2 and NANOG has been implicated in tumorigenicity and metastasis." (PMID 40626009, 2025). "On this basis, the present study investigated the clinical significance of PIK3CA and SOX2 gene amplification in early stages of laryngeal tumorigenesis by evaluating their predictive value for cancer risk assessment in 62 patients with laryngeal precancerous lesions." (PMID 38473941, 2024). "In addition, high Sox2 expression has been associated with poor prognosis and resistance to chemotherapy and radiotherapy, potentially as a result of its influence on cancer stem cell characteristics." (PMID 38473392, 2024). "In cancer, Sox2 is associated with “stemness” of cancer cells and prediction of poor outcome." (PMID 39103560, 2024). "Therefore, it is necessary to gain a comprehensive understanding of Sox2 regulation, its association with multiple signaling pathways in cancer, and its role in tumorigenesis and drug resistance." (PMID 38473392, 2024).
cancer (continued). "Thus, the levels of SOX2 should be precisely regulated in development, and altered expression of SOX2 can cause various diseases, including cancers and developmental disorders." (PMID 38396925, 2024). "Furthermore, combined PIK3CA and SOX2 amplification is emerging as a valuable and easy-to-implement tool for cancer risk assessment in patients with laryngeal precancerous lesions beyond current WHO histological grading." (PMID 38473941, 2024). "Recent findings have associated aberrant Sox2 expression with tumorigenesis in diverse cancers, including bladder cancer, breast cancer, colorectal cancer, gastric cancer, glioma, osteosarcoma, pancreatic cancer, prostate cancer, and skin squamous cell carcinoma." (PMID 38020885, 2023). "Some of the SOX genes have been associated with poor prognosis and cancer progression (SOX2, SOX5)." (PMID 37509311, 2023). "BTK silencing significantly decreased the expression of the Janus kinase 2 (JAK2)/signal transducer and activator of transcription 3 (STAT3) and, in consequence, reduced cancer cell viability via the SRY-box transcription factor 2 (Sox-2) and BCL-XL genes and increased susceptibility to cisplatin." (PMID 36903645, 2023). "Notably, the inactivation or loss of SOX2 expression has been linked to the development of highly invasive and malignant tumors." (PMID 38136437, 2023). "We investigated whether the SOX2 locus gains epigenetic features associated with active enhancers in cancer cells." (PMID 37738673, 2023). "SOX2 has previously been implicated with cancer development." (PMID 36932385, 2023). "Here, we investigated the mechanisms underlying SOX2 overexpression in cancer." (PMID 37738673, 2023). "Furthermore, elevated levels of SOX2 expression have also been associated with several cancers including breast, prostate, and pancreatic cancer." (PMID 37614497, 2023). "Such approaches could have therapeutic potential for controlling cell fate determination, suppressing cancer stemness and potentially treating diseases associated with dysregulated SOX2-p300 signaling." (PMID 37930832, 2023). "This work demonstrated that the CRC liver metastasis and cancer stemness regulated by ANGPTL1 shared the same pathway—ANGPTL1/Foxo3a/Sox2, but if there was an association between the two phenotypes is unknown." (PMID 36156125, 2022). "Nanog, Sox2, and c-Myc are transcription factors expressed in embryonic stem cells, but the aberrant expression of these molecules has been observed in various tumors and is associated with the development of cancer stem cell phenotypes." (PMID 35897737, 2022). "SOX2 expression has been implicated in various cancer stem cells." (PMID 35875180, 2022). "To discern the molecular underpinnings of our observed changes in stemness and invasion due to altered SNHG1 expression, we performed Western blotting using antibodies against several proteins implicated in cancer cell stemness and invasion, including SOX2, OCT4, CD133, and Rac1." (PMID 36077697, 2022). "SOX2 (Sex-determining region Y-box2) is a transcription factor with a key role in stem cell maintenance and has been associated with tumorigenesis in a variety of cancers." (PMID 36232992, 2022). "Additionally, Notch signaling is associated with SOX2 transcription, which seems to be reciprocal in some cancer types." (PMID 36118530, 2022). "Collectively, our research suggested that SOX2 might serve as a cancer‐promoting gene to identify high‐risk GBM patients, and SOX3 had the potential to be a prognostic biomarker for GBM patients." (PMID 34953010, 2022). "SOX2 is associated with the drug resistance of cancer stem cells (CSCs)." (PMID 36247876, 2022). "SOX2 is associated with disease progression, metastasis, and relapse in some cancer patients." (PMID 35059870, 2022). "FMOD and SOX2 might both ensure cancer cell self-renewal capacity (stemness), a property linked to the induction of EMT and required for metastatic outgrowth." (PMID 35737114, 2022).
cancer (continued). "SOX2 has been implicated in the development and progression of more than 20 human cancer types." (PMID 35454854, 2022). "FMOD has yet to be linked to VM but SOX2 was shown to facilitate VM of “stem-like” cancer cells." (PMID 35737114, 2022). "Moreover, a recent study identified a lncRNA, Cancer stem cell associated distal enhancer of SOX2 (CASCADES) as a novel epigenetic regulator for glioma cancer stem cells (GCSCs)." (PMID 33453053, 2021). "The de-repression of SOX2 has been associated with a wide range of cancer types, including GBM." (PMID 33805518, 2021). "NANOG, OCT4, and SOX2 mainly promote tumorigenesis by regulating the CSCs, and therefore high expression of these stem cell factors is associated with poorer outcomes in numerous cancers." (PMID 34573355, 2021). "Furthermore, Sox2 has been associated with tumorigenicity, illustrating its role in cancer stemness." (PMID 34195082, 2021). "Finally, SOX2 is a pluripotency factor strongly associated with cancer stem cells (CSCs), with a poor prognosis in several cancers, including CRC." (PMID 34503224, 2021). "SOX2 overexpression is associated with poor survival of cancer patients." (PMID 32728033, 2020). "Since SOX2 overexpression could stimulate cancer enhancing processes, it remains unclear why the loss of SOX2 expression is associated with malignant clinical phenotypes." (PMID 32098209, 2020). "Importantly, in cancer, SOX2 has been increasingly associated with a CSC phenotype in tumors from different tissues, namely of the ovary, prostate, lung, skin, and central nervous system." (PMID 32093282, 2020). "In addition to its critical roles during development, SOX2 has been implicated in over 20 different human cancers." (PMID 32998722, 2020). "Since SOX2 hypermethylation is associated with cancer development, taking exercise in heavily polluted areas may not be very helpful and therefore should be minimized." (PMID 32098209, 2020). "Further involving SOX2 in cancer stemness, elevated SOX2 expression associates with chemotherapy-resistance effects, induces stemness and endothelial-to-mesenchymal-transition gene signatures, and promotes clonogenicity and in vivo tumorigenicity in respective model systems." (PMID 31477842, 2020). "Moreover, Orai1 is capable of endowing non-tumorigenic immortalized oral epithelial cells with self-renovation, and concurrently enhances transcribing pluripotent and cancer stem cells-associated agents such as Nanog, Sox2, KLF4, Oct4, Zeb1, Bmi1, and Zeb2." (PMID 32280305, 2020). "The up-regulation of SOX2 is associated with increased level of cancer stem cell markers." (PMID 32111825, 2020). "SOX2, a pluripotency-associated transcription factor, is critical for embryonic and induced pluripotent stem cells 5; however, its expression is highly detrimental in at least 25 different cancers." (PMID 32194860, 2020). "Thus, the increase of SOX2 levels demonstrates the ability of ADO to partially change the GBM hallmarks promoting the expression of a gene associated with cancer aggressiveness." (PMID 33081024, 2020). "Finally, the prognostic value of Sox2 expression was investigated in FMCs, and revealed that Sox2 positivity was associated with shorter distant metastasis-free interval, disease-free survival, and cancer-specific survival." (PMID 33553286, 2020). "Interestingly, cancers of immanent high SOX2 expression often show intrinsically high mutations rates in PI3KCA or PTEN genes as well, thus suggesting functional connectivity between PI3K/AKT signaling and stemness-inductory roles of SOX2." (PMID 31477842, 2020).